MIR708 (microRNA 708)
Synonyms: hsa-mir-708; MIRN708
Gene: MicroRNA gene on chromosome 11 (79,402,022 to 79,402,109, reverse strand). Ensembl gene ENSG00000211997.
Gene Ontology:
Biological process: miRNA-mediated post-transcriptional gene silencing
Homologues: Orthologues: chimpanzee ptr-mir-708 (100% identical), macaque mml-mir-708 (98% identical), guinea pig MIR708 (95% identical), rat Mir708 (95% identical), mouse Mir708 (93% identical), pig ssc-mir-708 (89% identical), dog MIR708 (74% identical), rabbit MIR708 (74% identical).